SERPINA10 (serpin family A member 10)
Description:
Inhibits activity of the coagulation protease factor Xa in the presence of PROZ, calcium and phospholipids. Also inhibits factor XIa in the absence of cofactors.
Synonyms: PZI; ZPI
Tractability: Antibody: UniProt places it where antibodies can reach, with medium confidence; UniProt predicts a signal peptide or a membrane-spanning region; its Gene Ontology location is reachable by antibodies, with medium confidence. PROTAC: its protein half-life has been measured.
Gene: Protein-coding gene on chromosome 14 (94,278,767 to 94,293,295, reverse strand). Ensembl gene ENSG00000140093.
Subcellular location: Secreted
Subcellular location (Human Protein Atlas): Nucleoplasm; Cytosol; Predicted to be secreted
Pathways (Reactome):
Metabolism of proteins: Post-translational protein phosphorylation; Regulation of Insulin-like Growth Factor (IGF) transport and uptake by Insulin-like Growth Factor Binding Proteins (IGFBPs)
Hemostasis: Regulation of clotting cascade
Gene Ontology:
Molecular function: protein binding; serine-type endopeptidase inhibitor activity
Biological process: regulation of acrosome reaction; blood coagulation; liver regeneration
Cellular component: extracellular exosome; endoplasmic reticulum lumen; extracellular region
Genetic constraint (gnomAD): Loss-of-function variants: 25 observed, 30.88 expected, observed/expected ratio (o/e) 0.81, 90% interval 0.59 to 1.13. The upper end of that interval is the gene's LOEUF score, 1.13, which puts it in group 4 of 6, group 1 being the genes least tolerant of losing a copy. Missense variants: 521 observed, 567.81 expected, observed/expected ratio (o/e) 0.92, 90% interval 0.85 to 0.99. Synonymous variants: 207 observed, 216.1 expected, observed/expected ratio (o/e) 0.96, 90% interval 0.85 to 1.08.
Homologues: Orthologues: chimpanzee SERPINA10 (98% identical), macaque SERPINA10 (92% identical), guinea pig SERPINA10 (72% identical), rat Serpina10 (72% identical), mouse Serpina10 (71% identical), tropical clawed frog serpina10 (44% identical), zebrafish serpina10b (33% identical), zebrafish serpina10a (25% identical). Paralogues in human: SERPINA1 (29% identical), SERPINA7 (29% identical), SERPINA5 (29% identical), SERPINA3 (28% identical), SERPIND1 (28% identical), SERPINA9 (28% identical), SERPINA12 (26% identical), SERPINA4 (26% identical), SERPINB9 (26% identical), SERPINA6 (25% identical), SERPINB1 (25% identical), SERPINB7 (24% identical), and 24 more.
Diseases named in the same sentence as SERPINA10 in open-access papers:
SERPINA10 is named in the same sentence as 36 diseases in open-access papers, as found by Europe PMC text mining. Sharing a sentence is not in itself a finding about the gene and the disease. The quoted sentences say what the papers report.
thrombosis (4 papers, 2009 to 2019). "Mutations in the human gene SERPINA10, whose ortholog is located in this region, are associated with susceptibility to deep vein thromboses." (PMID 19909546, 2009). "Replication analysis of the rs2232710 (SERPINA10/ZPI gene) single nucleotide variant in patients with idiopathic deep vein thrombosis of lower extremities and heathy controls belonging to three independent cohorts: DVT-Milan, LETS and MEGA." (PMID 26982741, 2016).
COVID-19 (3 papers, 2022 to 2024). A disease caused by infection with severe acute respiratory syndrome coronavirus 2. "SERPINA10 is a known discriminating feature between severe and non-severe COVID-19, and can be used as a classifier of disease severity." (PMID 36930526, 2023).
lymphoma (2 papers, 2024 to 2025). A malignant (clonal) proliferation of B- lymphocytes or T- lymphocytes which involves the lymph nodes, bone marrow and/or extranodal sites. "In one study, individuals with lymphoma or multiple myeloma who carried factor V Leiden and SERPINA10 variants had higher VTE incidence; other data indicate that the coexistence of cancer and factor V Leiden variants synergistically increases VTE risk." (PMID 41164752, 2025). "Consistent with the findings of previous studies conducted in patients with solid tumours, our study also found that patients with lymphoma and MM who had two specific genetic variants (factor V Leiden and SERPINA10 variants) had a higher incidence of VTE." (PMID 38676874, 2024). "Moreover, there was a trend in genetic variant rs5985 (factor XIII) as a protective factor, and a trend to higher thrombotic risk in patients with factor V Leiden, rs2232698 variant (serpinA10), low total protein S activity, elevated D-dimer, aggressive lymphoma and treatment with dexamethasone." (PMID 38676874, 2024).
Sepsis (2 papers, 2023). Sepsis is defined as life-threatening organ dysfunction caused by a dysregulated host response to infection. "At the protein level, the proteins S100A8 and SERPINA10 were found to be biomarkers for severe burn patients with sepsis, and the results of scRNA-seq also revealed the important role of neutrophils in the early stages of severe burn injuries." (PMID 36659877, 2023). "The validation results suggested that S100A8 and SERPINA10 may serve as biomarkers for severe burn patients with sepsis." (PMID 36659877, 2023).
endometrial cancer (1 paper, 2023). Primary or metastatic malignant neoplasm involving the endometrium (mucous membrane that lines the endometrial cavity). "A four-marker panel comprising CSTA, S100A7, MMP9 and SERPINA10 predicted endometrial cancer with an AUC of 0.84 (0.77–0.92), sensitivity of 72.2%, specificity of 87.8%, NPV of 86.7% and PPV of 74.1%." (PMID 36807337, 2023).
neuroendocrine tumors (1 paper, 2011). "Eight genes (CHGA, CPE, ENO2, INSM1, PTPRN2, SERPINA10, and SLC18A1/2) that have been previously identified as markers of neuroendocrine tumors were confirmed in this study to be altered." (PMID 21853033, 2011).
ovarian carcinoma (1 paper, 2021). A malignant neoplasm originating from the surface ovarian epithelium. "Interestingly, an ECM-related gene expression, serpin family A member 10 (SERPINA10), was identified to be significantly positively correlated with overall survival (OS) and progression-free survival (PFS) in TCGA ovarian cancer cohort (all p < 0.05)." (PMID 34888242, 2021).
ovarian tumors (1 paper, 2018). "The significance of APOC2, APOC4, ORM1, SERPINA1, and SERPINA10 in differential diagnosis of ovarian tumors was not confirmed." (PMID 30065196, 2018).
parasitic infections (1 paper, 2025). "Meanwhile, genes related to cancer metastasis, such as Tns4, Neu1, Serpina10, and Trib3 (54, –, 57), as well as Mcpt1 and Mcpt2, which are associated with parasitic infections, were significantly upregulated after infection." (PMID 39727670, 2025).
thrombophilia (1 paper, 2016). A condition characterized by an abnormally high level of thrombi. "Several non-synonymous variants in the ZPI/SERPINA10 gene (henceforth called ZPI), in particular R67X and W303X mutations, have been identified in patients suffering from thrombophilia, even though other studies did not support these findings." (PMID 26982741, 2016).
tumor (5 papers, 2013 to 2024). "IHC staining showed that expressions of IGFBP4, TGFBI, and SERPINA10 proteins were detected in para-tumoral normal cells and tumor cells that were mostly located in the extracellular and cytosol compartments." (PMID 34888242, 2021). "The SERPINA10 protein, which belongs to the family of serine proteinase inhibitors, is involved in blood coagulation, complement activation, fibrinolysis, angiogenesis, inflammation, and tumor suppression." (PMID 23418487, 2013).
infection (1 paper, 2025). The state of being infected such as from the introduction of a foreign agent such as serum, vaccine, antigenic substance or organism. "Moreover, on 3 d and 7 d post-infection, DEGs related to gut diseases were significantly affected, particularly Ceacam10, Tns4, Neu1, Serpina10, and Npas2." (PMID 39727670, 2025).
SERPINA10 also shares sentences with these, for which no sentence is quoted: cancer (5 papers); cardiovascular disease (2); colon cancer (2); gastric cancer (2); acute lymphoblastic leukemia (1); amyloid diseases (1); emphysema (1); glomerulosclerosis (1); hematological disease (1); Hip dysplasia (1); Hypertension (1); inflammatory bowel disease (1); metastatic tumors (1); minimal change disease (1); multiple myeloma (1); nephrotic syndrome (1); neuroendocrine carcinoma (1); non-small cell lung carcinoma (1); pancreatic endocrine carcinoma (1); pancreatic endocrine tumors (1); pertussis (1); pulmonary fibrosis (1); small bowel neuroendocrine tumors (1); thrombotic disease (1).